CYTH1 (cytohesin 1)
Description:
Promotes guanine-nucleotide exchange on ARF1, ARF5 and ARF6. Promotes the activation of ARF factors through replacement of GDP with GTP. Plays an important role in membrane trafficking, during junctional remodeling and epithelial polarization, through regulation of ARF6 activity.
Synonyms: D17S811E; PSCD1; B2-1; cytohesin-1; SEC7
Tractability: Antibody: UniProt places it where antibodies can reach, with high confidence; its Gene Ontology location is reachable by antibodies, with high confidence. PROTAC: UniProt records ubiquitination sites on it; ubiquitination databases record sites on it; its protein half-life has been measured.
Chemical probes: SecinH3
Gene: Protein-coding gene on chromosome 17 (78,674,048 to 78,782,298, reverse strand). Ensembl gene ENSG00000108669.
Subcellular location: Cell membrane; Cytoplasm, cytosol; Cell junction, tight junction; Cell junction, adherens junction
Pathways (Reactome):
Vesicle-mediated transport: Intra-Golgi traffic
Gene Ontology:
Molecular function: guanyl-nucleotide exchange factor activity; protein binding
Biological process: regulation of cell adhesion; establishment of epithelial cell polarity; vesicle-mediated transport; regulation of ARF protein signal transduction
Cellular component: cytoplasm; plasma membrane; bicellular tight junction; cytoplasmic side of plasma membrane; cytosol; Golgi membrane; adherens junction
Genetic constraint (gnomAD): Loss-of-function variants: 17 observed, 61.57 expected, observed/expected ratio (o/e) 0.28, 90% interval 0.19 to 0.41. The upper end of that interval is the gene's LOEUF score, 0.41, which puts it in group 1 of 6, group 1 being the genes least tolerant of losing a copy. Missense variants: 334 observed, 521.3 expected, observed/expected ratio (o/e) 0.64, 90% interval 0.58 to 0.7. Synonymous variants: 172 observed, 189.86 expected, observed/expected ratio (o/e) 0.91, 90% interval 0.8 to 1.03.
Homologues: Orthologues: macaque CYTH1 (99% identical), chimpanzee CYTH1 (98% identical), guinea pig CYTH1 (98% identical), dog CYTH1 (98% identical), mouse Cyth1 (97% identical), rabbit CYTH1 (96% identical), pig CYTH1 (96% identical), rat Cyth1 (93% identical), zebrafish cyth1a (92% identical), zebrafish cyth1b (91% identical), tropical clawed frog cyth2 (90% identical), Drosophila melanogaster step (67% identical), and 1 more. Paralogues in human: CYTH3 (84% identical), CYTH2 (82% identical), CYTH4 (69% identical), ARFGEF2 (44% identical), ARFGEF1 (43% identical), GBF1 (37% identical), IQSEC1 (34% identical), IQSEC3 (30% identical), IQSEC2 (30% identical), PSD (26% identical), PSD3 (26% identical), PSD2 (24% identical), and 3 more.
Diseases named in the same sentence as CYTH1 in open-access papers:
CYTH1 is named in the same sentence as 25 diseases in open-access papers, as found by Europe PMC text mining. Sharing a sentence is not in itself a finding about the gene and the disease. The quoted sentences say what the papers report.
Hypertension (2 papers, 2022 to 2025). The presence of chronic increased pressure in the systemic arterial system. "For the hypertension and atrial fibrillation pairing, signals implicating shared causal variants were seen on chromosomes 4, 7, 11, and 17, in the genes FGF5, HOXA13, in the region spanning LSP1 to TNNT3 and that spanning CYTH1 to USP36 respectively." (PMID 40538118, 2025).
prostate carcinoma (2 papers, 2015 to 2020). A carcinoma that arises from epithelial cells of the prostate gland. "In prostate cancer, inhibiton of Cytohesin 1 by siRNA, reduces the pro-tumorigenic role of Insulin Growth Factor Receptor (IGFR) signaling, suggesting that this ARF GEF could be targeted to impair prostate cancer progression." (PMID 32426352, 2020).
colon cancer (1 paper, 2021). "The function of CYTH1 in colon cancer is poorly understood, we hypothesized that TNK2 is possible to work in synergy with CYTH1 or other co-expressed proteins." (PMID 34421982, 2021).
HCMV infection (1 paper, 2017). "Consistent with our previous report on HSV-1-infected mDCs, cytohesin-1 protein expression was not significantly affected by HCMV infection." (PMID 28484459, 2017). "In contrast, cytohesin-1 is not downregulated to a significant extent, even 36 h post-HCMV infection." (PMID 28484459, 2017).
neuroblastoma (1 paper, 2017). Neuroblastoma (NB) is the most common solid, extracranial childhood tumor. "However, to our knowledge, recurrent focal amplifications of MYC, ZFHX3, KRAS, RRAS2, and CYTH1 have not been reported in neuroblastoma primary tumors before." (PMID 28924153, 2017).
infection (3 papers, 2020 to 2025). The state of being infected such as from the introduction of a foreign agent such as serum, vaccine, antigenic substance or organism. "Consistent with HSV-1-infected mDCs, HSV-2-infected mDCs reveal only moderate regulation of cytohesin-1 protein expression later during infection." (PMID 31963276, 2020). "Consistent with our data obtained from mDC infection experiments, we observed a strong decrease in CYTIP protein expression in HSV-1- as well as HSV-2-infected HEK293T cells in the absence of any inhibitor, whereas cytohesin-1 protein levels remained stably expressed." (PMID 31963276, 2020).
cancer (2 papers, 2024 to 2025). A tumor composed of atypical neoplastic, often pleomorphic cells that invade other tissues. "Pathway analysis for rituximab-resistant cell lines showed enriched proteins (CYTH1, SEC24D, VPS25, and ARFGAP3) involved in membrane trafficking, which is a pathway mediating many processes and enzyme functions that cancer cells can use to promote tumorigenesis and drug responses." (PMID 41301803, 2025).
CYTH1 also shares sentences with these, for which no sentence is quoted: breast carcinoma (3 papers); Alzheimer disease (1); atherosclerosis (1); atrial fibrillation (1); autism (1); autistic spectrum disorders (1); Epileptic encephalopathy (1); hypertrophic cardiomyopathy (1); kidney damage (1); lung adenocarcinoma (1); neurological disease (1); ovarian carcinoma (1); Parkinson disease (1); pulmonary hypertension (1); Salmonella Infections (1); tuberculosis (1); tumor (1); X-linked intellectual disability (1).